MOSPD1 (motile sperm domain containing 1)
Description:
Plays a role in differentiation and/or proliferation of mesenchymal stem cells. Proposed to be involved in epithelial-to-mesenchymal transition (EMT). However, another study suggests that it is not required for EMT or stem cell self-renewal and acts during later stages of differentiation.
Synonyms: dJ473B4
Tractability: Antibody: UniProt predicts a signal peptide or a membrane-spanning region. PROTAC: ubiquitination databases record sites on it.
Gene: Protein-coding gene on chromosome X (134,887,613 to 134,915,470, reverse strand). Ensembl gene ENSG00000101928.
Subcellular location: Endoplasmic reticulum membrane; Golgi apparatus membrane
Subcellular location (Human Protein Atlas): Nucleoplasm; Vesicles
Gene Ontology:
Molecular function: protein binding
Biological process: negative regulation of transcription by RNA polymerase II; positive regulation of transcription by RNA polymerase II
Cellular component: cytoplasm; endoplasmic reticulum membrane; Golgi membrane; nucleus; perinuclear region of cytoplasm
Homologues: Orthologues: chimpanzee MOSPD1 (100% identical), macaque MOSPD1 (99% identical), guinea pig MOSPD1 (98% identical), mouse Mospd1 (97% identical), rat Mospd1l1 (97% identical), dog MOSPD1 (97% identical), pig MOSPD1 (97% identical), rat Mospd1 (93% identical), zebrafish mospd1 (79% identical), rabbit MOSPD1 (65% identical), tropical clawed frog mospd3 (37% identical), Caenorhabditis elegans C34D10.1 (34% identical).
Diseases named in the same sentence as MOSPD1 in open-access papers:
MOSPD1 is named in the same sentence as 4 diseases in open-access papers, as found by Europe PMC text mining. Sharing a sentence is not in itself a finding about the gene and the disease. The quoted sentences say what the papers report.
autism (1 paper, 2021). Persistent deficits in social interaction and communication and interaction as well as a markedly restricted repertoire of activity and interest as well as repetitive patterns of behavior. "Four genes cg23920016 (NOS1AP), cg24274662 (MOSPD1), cg26017408 (AFAP1L2) and cg16930349 (GRIPAP1) identified based on predictive ability for autism using AI analysis." (PMID 34260616, 2021).
ovarian carcinoma (1 paper, 2012). A malignant neoplasm originating from the surface ovarian epithelium. "MOSPD1 has been implicated in mesenchymal cell differentiation and is upregulated in ovarian cancer." (PMID 22992265, 2012).
cancer (1 paper, 2015). A tumor composed of atypical neoplastic, often pleomorphic cells that invade other tissues. "Similarly, “cancer-specific” escapees generally exhibited higher enrichment at their TSS in the cell lines where they escaped compared to HMECs with a few exceptions (e.g., CFP, FLNA, and MOSPD1 in MDA-MB-436 cells displayed no obvious differences in TSS profiles)." (PMID 25653311, 2015).
MOSPD1 also shares sentences with these, for which no sentence is quoted: breast carcinoma (1 paper).